ZAN (zonadhesin)
Description:
Binds in a species-specific manner to the zona pellucida of the egg. May be involved in gamete recognition and/or signaling.
Tractability: Antibody: UniProt places it where antibodies can reach, with medium confidence; UniProt predicts a signal peptide or a membrane-spanning region; its Gene Ontology location is reachable by antibodies, with medium confidence. PROTAC: ubiquitination databases record sites on it.
Gene: Protein-coding gene on chromosome 7 (100,733,595 to 100,797,797, forward strand). Ensembl gene ENSG00000146839.
Subcellular location: Cell membrane
Gene Ontology:
Molecular function: extracellular matrix structural constituent
Biological process: binding of sperm to zona pellucida; cell-cell adhesion
Cellular component: extracellular matrix; plasma membrane; membrane
Genetic constraint (gnomAD): Loss-of-function variants: 251 observed, 264.54 expected, observed/expected ratio (o/e) 0.95, 90% interval 0.86 to 1.05. The upper end of that interval is the gene's LOEUF score, 1.05, which puts it in group 4 of 6, group 1 being the genes least tolerant of losing a copy. Missense variants: 3,258 observed, 3,417.3 expected, observed/expected ratio (o/e) 0.95, 90% interval 0.93 to 0.98. Synonymous variants: 1,311 observed, 1,316.7 expected, observed/expected ratio (o/e) 1, 90% interval 0.95 to 1.04.
Homologues: Orthologues: chimpanzee ZAN (89% identical), pig ZAN (60% identical), dog ZAN (60% identical), rabbit ZAN (53% identical), mouse Zan (41% identical), rat Zan (40% identical), zebrafish zanl (29% identical). Paralogues in human: FCGBP (24% identical), MUC5AC (14% identical), OTOG (13% identical), MUC5B (13% identical), OTOGL (13% identical), VWF (13% identical), TECTA (11% identical), KCP (9% identical), MUC19 (9% identical), MUC6 (9% identical), MUC2 (8% identical), CRIM1 (7% identical), and 7 more.
Diseases named in the same sentence as ZAN in open-access papers:
ZAN is named in the same sentence as 2 diseases in open-access papers, as found by Europe PMC text mining. Sharing a sentence is not in itself a finding about the gene and the disease.
kidney chromophobe carcinoma (1 paper, 2025).
ZAN also shares sentences with these, for which no sentence is quoted: biliary tract cancer (1 paper).